SIRT3 (sirtuin 3)
Diseases named in the same sentence as SIRT3 in open-access papers (continued):
Sharing a sentence is not in itself a finding about the gene and the disease.
diabetes (continued). "In diabetic IRI model, Dapagliflozin can effectively improve FAO dysfunction and inhibit abnormal glycolysis by activating SIRT3/PGC-1α signaling pathway, thus providing renal protection." (PMID 41451126, 2025). "Furthermore, since SIRT3 is expressed in major organs such as the brain, heart, and kidneys, research on SIRT3 may provide insights into the mechanisms and treatment of comorbidities such as stroke with diabetes and stroke combined with coronary heart disease." (PMID 40969935, 2025). "Consistently, analysis of TEM images also demonstrated that diabetes induction dramatically increased MAM formation in the hippocampus, and that this effect was reversed by SIRT3 overexpression." (PMID 37481555, 2023). "Interestingly, SIRT3 is called a longevity gene due to its negative correlation with hypertension, obesity and diabetes, and insufficiency of SIRT3 acts as a contributor to cardiac fibrosis, which strongly implicates SIRT3 as a crucial mediator between aging-associated diseases and cardiac fibrosis." (PMID 37408261, 2023). "SIRTs activator, resveratrol, has been reported to improve diabetes-provoked cardiac dysfunction via activation of SIRT1 and SIRT3." (PMID 34071497, 2021). "Sundaresan and colleagues reported that SIRT3 was decreased, accompanied by increased percentage of apoptotic cells in STZ-induced diabetes mouse model." (PMID 34616362, 2021). "As it does in other diseases, SIRT3 activates MnSOD2 and IDH2 to remove harmful ROS and activates FOXO3a to induce cell-protective autophagy to improve obesity and diabetes." (PMID 32724473, 2020). "A study indicated that TGR5 activation inhibited kidney disease in obesity and diabetes by inhibiting oxidative stress via promoting sirtuin 1 (SIRT1) and sirtuin 3 (SIRT3) expression." (PMID 33298860, 2020). "The expression and activity of Sirt1, Sirt2, Sirt3, and Sirt5 is reduced in a streptozotocin- (STZ-) induced type 1 diabetes mellitus (T1DM) model, while the level of Sirt3 is increased in a high-fructose diet-induced T2DM model." (PMID 32256959, 2020). "Pre-diabetes are known to downregulate PGC-1α protein levels, thus we evaluated the effects of sucrose diet intake on Sirt3 and PGC-1α protein levels." (PMID 27634872, 2016). "After adjustment for age, sex, diabetes mellitus, hypertension, cognitive status (MMSE scores), and number of co morbidities, serum SIRT1, SIRT2, and SIRT3 concentrations were found to be significantly lower in frail as compared to nonfrail patients." (PMID 25100619, 2014). "Hence, SIRT1 and SIRT3 have been researched in metabolic diseases, such as type 2 diabetes mellitus (DM), fatty liver, and heart diseases." (PMID 24073959, 2013). "SIRT1, SIRT3, and SIRT6 activation may be a new treatment strategy for various metabolic diseases including diabetes, obesity, and osteoporosis." (PMID 41304967, 2025). "We then detected the expression of Sirt3 in oocytes and the results showed that NMN could increase the Sirt3 expression which is downregulated in IVM oocytes of the mouse with diabetes." (PMID 38653987, 2024). "The protein expression of SIRT1/3 was significantly elevated in CF upon HG exposure, yet, only the protein expression of SIRT3 was restored by silencing NAP1L2, indicating that NAP1L2 might affect SIRT3 to affect CF functions in diabetes." (PMID 37993768, 2023). "For example, according to some researchers, in type 2 diabetes mellitus (T2DM) model rats, Sirtuin3 (SIRT3), a nicotinamide adenine dinucleotide + (NAD+)-dependent HDAC, deacetylates forkhead box class O3a (FoxO3a) and subsequently inhibits FoxO3a phosphorylation, ubiquitination, and degradation." (PMID 37152435, 2023). "In summary, our study demonstrates a previously unknown relationship between SIRT3 and MAM coupling in diabetes-induced cognitive dysfunction." (PMID 37481555, 2023).
diabetes (continued). "Indeed, co-immunoprecipitation assay results showed that enhancement of SIRT3 expression by HKL decreased the interaction between IP3R, GRP75 and VDAC1 in diabetes model mice." (PMID 37481555, 2023). "Icariin has a cardioprotective effect in high-glucose-treated cardiomyocytes via upregulating apelin and SIRT3 expression, which can reverse diabetes-induced mitochondrial dysfunction; however, it did not affect the activity of SIRT3 in apelin silence samples." (PMID 35355561, 2022). "Interestingly, several studies have shown that SIRT3 promoted autophagy by regulating AMPK-mTOR signaling, thereby ameliorating acute kidney injury, ischemic neuronal injury, diabetes and osteoarthritis." (PMID 36192726, 2022). "Absence of SIRT3 accelerates the progression of diabetes development and triggers other complications including cardiac problems and interstitial fibrosis." (PMID 32722262, 2020). "Sirtuin 3 (Sirt3) is a member of NAD+-dependent deacetylase; it is a key regulator of the mitochondrial respiratory chain and plays an important role in the pathophysiology of various diseases, such as diabetes and metabolic syndrome, and aging." (PMID 32089781, 2020). "In the present work, we confirmed that SIRT-3 protein expression levels were significantly higher in patients with diabetes than those without diabetes, in a larger study population." (PMID 30917505, 2019). "So far, the direct link between APLN and Sirt3 in the regulation of myocardial angiogenesis in post-MI diabetes has not been reported." (PMID 25311234, 2015). "Irrespective of various categories such as differences in age (>60), sex, diabetes mellitus, hypertension, and number of comorbidities, the SIRT1 and SIRT3 levels were still significantly lower in case of frail as compared to nonfrail; however, in case of SIRT2, the differences were not significant." (PMID 25100619, 2014). "Honokiol, a SIRT3 agonist, has the potential to improve implant osseointegration in patients with diabetes, because it might help to reverse the negative effects of diabetes on bone repair." (PMID 36648334, 2023). "We speculated that SIRT3 plays its protective role through SIRT3‐GSK3β deacetylation pathway and antioxidant system, respectively, in diabetes mice, and ROS appears not be a mediator in this deacetylation pathway." (PMID 33107080, 2021). "In fact, low levels of SIRT3 were observed in the muscle of mice models of types 1 and 2 diabetes mellitus (DM), in line with data obtained in testes of prediabetic rats that demonstrated decrement of both PGC-1α and SIRT3 levels." (PMID 32377289, 2020). "Additionally, the persistent exposure of diabetic cells to high glucose concentrations (25 mM) promoted the upregulation of caveolin-1, N-cadherin, SIRT3, SIRT7 and lactate levels, suggesting that long-term diabetes may promote cell proliferation." (PMID 30093732, 2018). "We also evaluated the expression of SIRT-3 and p-mTOR in non-cancerous adjacent liver tissue of HCC patients with diabetes and/or metabolic syndrome, to verify whether their positive expression was limited to cancerous tissue." (PMID 30917505, 2019).
Obesity (93 papers, 2010 to 2025). Accumulation of substantial excess body fat. "Here, the effects and underlying mechanisms of endothelial SIRT3 in modulating the whitening of BAT during obesity progression were explored." (PMID 40520025, 2025). "In obese in vivo models and individuals with obesity, the expression of Cs, Sirt3, and Prkaa2 is reduced and is associated with mitochondrial dysfunction." (PMID 39269560, 2025). "In general, we unveil a novel pharmacological strategy for combating obesity-associated adipose tissue dysfunction by delineating a previously unrecognized mechanism through which ALM activates SIRT3 to orchestrate FUNDC1-mediated mitophagy." (PMID 41372934, 2025). "AR-C17 has also been demonstrated to ameliorate obesity-associated skeletal muscle mitochondrial dysfunction through Sirt3-mediated mitophagy." (PMID 38613012, 2024). "In a separate study, sirt-3-deficient mice fed a chronic HFD developed obesity, insulin resistance, and steatohepatitis more rapidly than wild-type mice." (PMID 37759566, 2023). "HFD in SIRT3 deficient mice exacerbates obesity, IR, hyperlipidemia, hepatic steatosis, and inflammation, however, adenovirus overexpressing SIRT3 rescued this phenotype." (PMID 37507803, 2023). "Whereas SIRT3 SUMOylation deficiency overcomes high-fat diet (HFD) induced obesity in mice under fasting conditions has been documented by our previous study." (PMID 35955415, 2022). "The mitochondrial deacetylase enzyme Sirt3 has been found to decrease such oxidative stress and abnormal fatty acid oxidation, two processes that have both been implicated in diabetes and obesity." (PMID 35409099, 2022). "Although the molecular mechanism for SIRT3 regulation of endothelial insulin sensitivity remains to be elucidated, this protective role of SIRT3 in obesity has been observed to be linked with reduced mitochondrial ROS production." (PMID 35369299, 2022). "SIRT3 deficiency leads to endothelial dysfunction and insulin resistance in humans and rodents with obesity." (PMID 34829803, 2021). "It has been shown that obesity can disrupt the function of mitochondria and is a major cause of Sirt3 reduction in oocytes of obese mice." (PMID 33841532, 2020). "SIRT1 is directly implicated on the levels of SIRT3 whose functions appear reduced in aging and in obesity." (PMID 32335547, 2020). "Sirt3 deficiency has been associated with insulin resistance, obesity, and increase in proinflammatory cytokines and inflammation." (PMID 33191653, 2020). "From a therapeutic standpoint, SIRT3 loss-of-function variant DCM patients lose the empagliflozin-protective effects, since SIRT3 is implicated in modern world diseases, such as aging, circadian disturbance, and obesity." (PMID 33138323, 2020). "SIRT3-deficient mice fed a chronic high-fat diet (HFD) develop accelerated obesity, insulin resistance, and steatohepatitis compared with WT mice." (PMID 29581157, 2018). "SIRT3 deficiency and resultant mtROS overproduction contribute to endothelial dysfunction in obesity." (PMID 27000941, 2016). "In conclusion, Our results showed that SIRT3 deficiency and resultant mtROS overproduction lead to endothelial insulin resistance and contribute to endothelial dysfunction in obesity." (PMID 27000941, 2016). "In humans with obesity and in diet-induced obese mice, SIRT3 deficiency induces endothelial insulin resistance, increases mitochondrial ROS, and blunts insulin-stimulated vasorelaxation, linking SIRT3 loss to early vascular metabolic dysfunction." (PMID 41465170, 2025). "Therapeutic interventions that either promote SIRT3 activity or enhance LC secretion in adipocytes could be a promising strategy to treat obesity-associated insulin resistance and metabolic disorders." (PMID 40368890, 2025). "Although most studies have explored the regulatory role of SIRT3 on age-related bone loss, this finding indicates that SIRT3 may also have a unique role in obesity-induced OP." (PMID 38192409, 2023).
Obesity (continued). "SIRT3 is able to prevent the loss of brown AT during obesity and metabolic disorders." (PMID 36505468, 2022). "However, germline SIRT3 knockout mice exhibit an enhanced susceptibility to HFD-induced obesity, and display systemic metabolic complications, such as glucose intolerance, insulin resistance and NALFD." (PMID 33806509, 2021). "There are seven known sirtuins (SIRT1-7), of which SIRT3 is known to be particularly important in the context of aging-related diseases such as cancer, cardiovascular disease, hearing loss, type 2 diabetes, and obesity." (PMID 33867853, 2021). "Taken together, our findings suggest that SIRT3 positively regulates endothelial insulin sensitivity and show that SIRT3 deficiency and resultant increased mtROS contribute to vascular dysfunction in obesity." (PMID 27000941, 2016). "Therefore, effective SIRT3 activators targeting AT could be promising drug candidates against obesity-associated metabolic disorders." (PMID 40368890, 2025). "SIRT3 functions as a deacetylase responsible for the majority of mitochondrial lysine acetylation 41, 42, and it has been linked to functional roles in a range of pathogenic contexts such as cancer, obesity, type 2-diabetes, cardiovascular disease, and hearing loss." (PMID 33867853, 2021). "SIRT3 can be strongly associated with the maintenance of metabolic regulation based on the finding that loss of Sirt3 in the germline of mice leads to accelerated development of obesity, hepatic steatosis and insulin resistance upon high-fat diet (HFD) feeding." (PMID 25907989, 2015). "In obesity, SIRT3 expression is reduced, resulting in the hyperacetylation of mitochondrial proteins, thereby compromising mitochondrial integrity and function." (PMID 41304967, 2025). "Under prolonged HFD exposure, SIRT3 knockout (SIRT3KO) mice exhibited accelerated obesity, impaired glucose homeostasis, and insulin resistance, along with pronounced hepatic steatohepatitis and fibrosis, compared to WT controls." (PMID 41465170, 2025). "Second, gain of function needed further validation to verify the therapeutic effects of endothelial SIRT3 in treating obesity." (PMID 40520025, 2025). "Sirtuin-3 (SIRT3) significantly improves mitochondrial protein function, and SIRT3 suppression is a key component of metabolic syndrome predisposing to obesity." (PMID 41465437, 2025). "Here we found global endothelium-specific Sirt3 knockout accelerated the diet-induced obesity process, accompanied by obvious BAT whitening and pathological WAT expansion." (PMID 40520025, 2025). "SIRT3 knockout mice on a high-fat diet exhibited accelerated obesity, hyperlipidemia, and insulin resistance compared to the wild type mice." (PMID 41304967, 2025). "SIRT3 expression is downregulated in obese patients, and deletion of SIRT3 leads to increased mitochondrial oxidative stress, reduced energy expenditure and worsened glucose metabolism, resulting in accelerated obesity under a high-fat diet (HFD) feeding." (PMID 40368890, 2025). "In summary, our study uncovered a novel role of adipocyte-expressed SIRT3 in mitigating infiltration and pro-inflammatory polarization of macrophages, thereby attenuating AT inflammation and protecting against obesity-related insulin resistance." (PMID 40368890, 2025). "Other research has described the expression of SIRT3 in oocytes under different physiological and pathological conditions, touching upon reproductive aging, obesity, and polycystic ovary syndrome (PCOS)." (PMID 39329773, 2024). "In obesity studies, it has been shown that SIRT3 can act as a positive regulator of insulin sensitivity, while SIRT3 expression is down-regulated in obesity." (PMID 39458556, 2024). "SIRT1 overexpression has also been documented to significantly decrease the hyperacetylation of SIRT3 and enhance the activity of SIRT3 in obesity and aging-related diseases." (PMID 38767771, 2024).
Obesity (continued). "It was found that the ROS content was increased and the SIRT3 expression was decreased in oocytes of the mouse with obesity." (PMID 38653987, 2024). "Decrease of SIRT3 in failing hearts from patients with obesity and metabolic syndrome leads to CypD hyperacetylation, mitochondrial permeability transition pore opening, and cardiac dysfunction." (PMID 37143582, 2023). "This is not only related to the inhibition of OS by SIRT3 but also the inhibition of obesity by SIRT3." (PMID 36374406, 2023). "The p300/CBP family and SIRT3/SIRT6 are involved in the process of obesity, and the histone acetylation level is positively correlated with adipogenic differentiation." (PMID 37143582, 2023). "This study aimed to elucidate Sirt3′s molecular mechanism in regulating insulin sensitivity in adipocytes that can contribute to the effort of targeting Sirt3 for the treatment of obesity and type 2 diabetes." (PMID 35409099, 2022). "SIRT3 plays an important role in various chronic diseases, such as obesity, cardiovascular disease, NASH, and NAFLD." (PMID 35721117, 2022). "Studies in models of obesity reflect that SIRT3 can act as a positive regulator of insulin sensitivity in human and mice endothelial cells." (PMID 35369299, 2022). "SIRT3 germline knockout mice develop various forms of metabolic dysfunctions at an accelerated rate, including obesity, hepatic steatosis, and insulin resistance." (PMID 35571098, 2022). "Sirt3-knockout mice fed a high fat diet showed accelerated obesity, metabolic syndrome, glucose intolerance, and insulin resistance." (PMID 35409099, 2022). "-regulates the process of acetylation of mitochondrial proteins through SIRT;-therapeutic agent against obesity by activating SIRT3 in cells." (PMID 36614171, 2022). "An increased SIRT3 expression increases cellular respiration whilst decreasing the amount of ROS, and obesity correlates with a decreased SIRT3 expression in the brown adipose tissue of obese mice." (PMID 33806509, 2021). "SIRT3 expression can be reduced by palmitic acid, which levels increase during obesity, lea-ding to oxidative stress and apoptosis, and to impaired intestinal permeability." (PMID 33806509, 2021). "During hypoxia in the adipose tissue, which— —is frequently observed in obesity, SIRT3 expression is downregulated in the visceral adipose tissue." (PMID 33806509, 2021). "In agreement with previous data regarding the protective role of Sirt3 and ovary hormones in obesity, HFD-fed ovx KO females displayed the highest body weight gain, but interestingly, lower lipid accumulation than sham mice." (PMID 33924115, 2021). "An increase of SIRT3 levels can preserve heart function and heart capillary density during obesity, and activation of the SIRT3/FOXO3 pathway can protect the heart from HFD-induced oxidative stress." (PMID 33806509, 2021). "The hyperacetylation‐related dysfunction of oxidative phosphorylation and fatty acid β‐oxidation, as well as insulin resistance and obesity, was found in Sirt3 knockout mice." (PMID 33421349, 2021). "We then further investigated the effects of HFD-induced obesity on female SIRT3 ECKO mice and the potential sex differences." (PMID 33371209, 2020). "In models of obesity, EETs have been shown to activate PGC-1α, resulting in preserved mitochondrial structural and functional proteins associated with preserved Sirt-3 expression." (PMID 32116760, 2020). "Collectively, the current study demonstrates that the anti-obesity effect of myricetin was mediated through the upregulation of Sirt3 expression and the subsequent activation of mitochondrial fatty acid oxidation." (PMID 30545041, 2018). "The current study demonstrated that myricetin reduced the lipid content of adipocytes and exerted anti-obesity effects through the upregulation of Sirt3 expression." (PMID 30545041, 2018). "Previous studies have highlighted the anti-inflammatory role of SIRT3 in obesity-related diseases, including insulin resistance." (PMID 30574122, 2018).